USP1 (ubiquitin specific peptidase 1)
Diseases named in the same sentence as USP1 in open-access papers (continued):
Sharing a sentence is not in itself a finding about the gene and the disease.
cancer (78 papers, 2011 to 2026). A tumor composed of atypical neoplastic, often pleomorphic cells that invade other tissues. "An imbalance of Th17 cells and Tregs is strongly associated with cancer progression; strikingly, USP1 is reported to be a vital regulator of the differentiation of Th17 cells and Tregs." (PMID 38715050, 2024). "We demonstrated that the loss of USP1 promoted γH2AX expression, induced pro-apoptotic factors, and subsequently increased cancer sensitivity to cisplatin treatment both in vitro and in vivo." (PMID 35966591, 2022). "USP1 promotes MAST1-mediated MEK1 activation as an underlying mechanism that contributes to cisplatin-resistance in cancers." (PMID 35966591, 2022). "Collectively, these studies demonstrate that USP1 can be used as a potential therapeutic target for cancer; however, its underlying mechanism remains to be further explored." (PMID 36357365, 2022). "The elevated USP1 level was associated with short overall survival of patients and with advanced stages of cancers." (PMID 31921663, 2019). "Around forty cancer-associated USP1 mutations were included in the COSMIC database by September 2013." (PMID 25744535, 2015). "These include the role of the serine 313 phosphorylation site, the relative contribution of different USP1 sequence motifs to UAF1 binding, and the potential effect of cancer-associated mutations on USP1 regulation by autocleavage." (PMID 25744535, 2015). "In addition, studies have revealed that increased USP1 expression is associated with a poorer prognosis in different cancer types." (PMID 39735674, 2025). "Inhibiting USP1 could be a potential therapeutic strategy for cancers with BRCA1-deficient cells, especially those resistant to PARP inhibitors." (PMID 40001543, 2025). "Therefore, we discovered that survivin is a specific substrate of USP1 and is associated with the inhibition of USP1-mediated sensitization of cancer cells to anti-cancer drugs." (PMID 36153316, 2022). "Although USP1 is a regulator of diverse substrate and cellular biological processes, USP1-targeted substrates and the underlying mechanisms of cancer cell death remain unclear." (PMID 36153316, 2022). "USP1 had low prevalence in gene mutation, but was elevated in several human cancers." (PMID 33123289, 2020). "USP1 over-expression is associated with cancer aggressiveness in multiple tumor types." (PMID 28881649, 2017). "On the other hand, our results support the view that USP1 autocleavage may occur in cis, and can be altered by a cancer-associated mutation." (PMID 25744535, 2015). "The functional effect of these cancer-associated USP1 mutations remains to be investigated." (PMID 25744535, 2015). "We next tested the ability of these cancer-associated USP1 mutants to deubiquitinate PCNA." (PMID 25744535, 2015). "It remains to be elucidated if USP1 autocleavage occurs in cis (intramolecularly) or in trans (intermolecularly) and, more importantly, if USP1 autocleavage could be altered by cancer-associated USP1 mutations that cluster around the G670/G671 motif." (PMID 25744535, 2015). "Thus, USP1 is associated with multiple diseases including cancer." (PMID 34873426, 2021). "In addition, USP1 is linked to treatment response in cancers." (PMID 32951278, 2020). "Finally, our results support the view that USP1 autocleavage may occur in cis, and show that the balance of USP1 autocleavage can be disrupted by a cancer-associated mutation." (PMID 25744535, 2015). "The deubiquitinating enzyme, ubiquitin-specific protease 1 (USP1), is overexpressed in various tumor types, making it a promising target for cancer therapy." (PMID 42017803, 2026). "The field of USP1 inhibitors is rapidly evolving, and these clinical trials will provide crucial data for this novel therapeutic approach in cancer management, particularly for patients with HRD-positive tumors and those resistant to PARP inhibitors." (PMID 40001543, 2025).
cancer (continued). "USP1 inhibitors represent a promising class of drugs targeting DNA damage repair mechanisms, particularly in homologous recombination deficient (HRD) cancers." (PMID 40001543, 2025). "Several USP1 inhibitors have been developed in recent years, demonstrating potential as anti-cancer agents." (PMID 40136409, 2025). "High expression of USP1 in DLBCL has been found to be associated with a poorer prognosis, while inhibition with Pimozide or knockdown of USP1 has been shown to reduce cancer cell growth and induce cell cycle arrest." (PMID 40001543, 2025). "Considering its observed overexpression and crucial role in various aspects of cancer treatment, targeting USP1 emerges as a promising therapeutic strategy for SCLC." (PMID 39735674, 2025). "These collective studies indicate that USP1 holds potential as a promising target for cancer therapy." (PMID 40136409, 2025). "USP1 inhibitors have recently emerged as potential anti-cancer agents and we validated the deubiquitinase activity of USP1–WDR48 as a robust synthetic lethal partner for MSC778 using both genetic and pharmacological approaches." (PMID 41359388, 2025). "Many research studies have revealed the role and mechanisms of USP1 in cancer growth and metastasis." (PMID 39735674, 2025). "By analysis of The Cancer Genome Atlas database, the mRNA level of USP1 was positively correlated with ATG14, UVRAG, and PIK3C3 (VPS34)." (PMID 39814232, 2025). "KSQ‐4279, an USP1 inhibitor in clinical trial, widely reversed multidrug resistance in refractory cancers by competing for the drug‐binding pockets of ABCB1/ABCG2/ABCC1 and blocking chemotherapeutic drugs’ efflux." (PMID 41328326, 2025). "USP1 rapidly became an emerging therapeutic target of malignant tumors with the emergence of the concept “Synthetic Lethality”, which indicates the great prospect of USP1 inhibitors in combination therapy." (PMID 41328326, 2025). "In various types of cancer, USP1 is often overexpressed and mediates the stabilization of inhibitors of DNA binding and cell differentiation (ID proteins family) to regulate tumor proliferation, metastasis and apoptosis." (PMID 38366146, 2024). "Previously, we reported that USP1 regulated the MAST1-mediated MEK pathway in cisplatin-resistant cancer cells." (PMID 38498222, 2024). "USP1 is aberrantly expressed in various human cancers and participates in tumor initiation and progression, holding significant implications for targeted cancer therapy." (PMID 39062505, 2024). "A reduction in USP1 levels inhibits cancer cell proliferation, suppresses metastasis, and sensitizes cancer cells to irradiation and chemotherapeutic drugs in various cancers." (PMID 39513905, 2024). "Recent studies have suggested that USP1 contributes to tumorigenesis and the progression of various cancers." (PMID 39513905, 2024). "USP1 is one of the well-characterized USPs, and its inhibition plays an important role in treating cancers." (PMID 39513905, 2024). "Our findings reveal that circUSP1 plays a crucial role in promoting cancer by interacting with and stabilizing HuR protein, leading to an increase of USP1 and Vimentin at the post-transcriptional level." (PMID 38366146, 2024). "ML323, a selective USP1 inhibitor, was suggested to exert antineoplastic effects on several cancer types." (PMID 38715050, 2024). "A variety of DUB inhibitors have been verified to be effective in malignant tumors, especially those targeting USP1, USP7, and UPS14, displaying great potential for clinical application, such as ML323, SJB3-019A, KSQ-4279, Compound 4, FT671 and VLX1570." (PMID 37369659, 2023). "USP1, in particular, has been identified as a promising target for cancer‐therapy, for a variety of tumours, including: breast, ovarian, colorectal, Non‐small Cell Lung, bone and glioma cancers." (PMID 36385258, 2023). "A recent study revealed that the stability of MAST1 is also enhanced by the deubiquitinase USP1 in cisplatin-resistant cancer cells." (PMID 37569286, 2023).
cancer (continued). "Several inhibitors have been verified as effective in battling malignant tumors, especially those targeting USP1, USP7 and USP14, which display great potential for clinical application." (PMID 37369659, 2023). "It was proved that targeting USP1 (Ubiquitin-specific protease 1) ultimately increased the sensitivity of tumor cells to cisplatin and enhanced the anti-cancer efficacy." (PMID 37291676, 2023). "Combinations of pyridostatin with WEE1 and USP1 inhibitors have recently been reported to act synergistically in inhibiting growth of cancer cells in vitro." (PMID 35107878, 2022). "Further data set analyses with the cancer genome atlas (TCGA) demonstrated that a high USP1 expression level predicts poor overall survival of PDAC patients." (PMID 35663242, 2022). "In our study, to identify new substrates of USP1 in cancer cell death, we investigated alterations in the major regulators of apoptosis using genetic (siRNA) and pharmacological inhibitors." (PMID 36153316, 2022). "Several USP1 inhibitors sensitizes cancer cell to platinum-, DNA-damaging-, and radiation-induced death." (PMID 36153316, 2022). "The high expression of USP1 corresponded with MAST1 protein expression in the cancer cell lines we tested." (PMID 35966591, 2022). "Many studies have reported the involvement and function of USP1 in cancer metastasis and proliferation." (PMID 36153316, 2022). "The high scores of MAST1 mRNA corresponded with USP1 mRNA level across a wide range of cancer types." (PMID 35966591, 2022). "These tumours rely on ATR, CHK1 and also USP1 activity for their survival, suggesting that targeting USP1 would be an alternative strategy for treating cancers with high levels of MYC-induced replication stress." (PMID 36240066, 2022). "Our dual screening approach based on a CRISPR/Cas9 system identified USP1 as a novel and bona fide candidate that governs cisplatin-resistance in cancer." (PMID 35966591, 2022). "Implications for the targeting of USP1 activity via protein-DNA trapping in cancer therapy are discussed." (PMID 35365626, 2022). "Because USP1 is highly expressed in many cancers, dysregulation of USP1 contributes to cancer therapy." (PMID 36153316, 2022). "USP1 has been shown overexpressed in multiple cancers, which indicate its important biomarker in tumorigenesis and development." (PMID 34873426, 2021). "Deubiquitylating enzyme ubiquitin-specific protease 1 (USP1) has been reported to be aberrantly overexpressed in cancers, and it plays a critical role in regulating various cellular processes, such as cell proliferation, apoptosis, and cell differentiation." (PMID 33390793, 2021). "In this study, RNA-seq results showed the enrichment of 3 stem cell-related signaling in the top 20 pathways, including Wnt signaling, Notch signaling, and Hedgehog signaling, indicating a critical role for USP1 in cancer cell stemness." (PMID 33102219, 2020). "High-throughput sequencing (The Beijing Genomics Institute, Beijing, China) was used to identify USP1-regulated pathways in HCC and determine how USP1 affects cancer cell survival and metastasis." (PMID 33102219, 2020). "The deubiquitinating enzyme USP1 is the most well-studied DUB and it has been implicated in many cancer types." (PMID 33114077, 2020). "To identify the role of USP1 in cancer cell survival in the blood, we obtained single CTCs from peripheral vein blood and extracted RNA using a single-cell-to-CT quantitative reverse transcription-PCR (qRT-PCR) kit." (PMID 33102219, 2020). "Regarding cancer stage and tumour grade, we found that USP1 was overexpressed in stages 1‐3 and grades 1‐4." (PMID 32951278, 2020). "FLG interacts with MCL1, USP1, C21orf59, MAK, and KIR3DS1 and mucin interacts with ERBB3, SNAI1, TWIST1, TWIST2, and CDH2, all of which, IPA predicted to be associated with cancer." (PMID 31058088, 2019).
cancer (continued). "For our studies, we used MK1775 (AZD1775), a WEE1 kinase inhibitor that is being clinically evaluated in several cancers, and pimozide a potent USP1-targeting drug." (PMID 31287417, 2019). "The USP1-selective inhibitor ML323 sensitizes cancer cells to cisplatin, demonstrating that USP1 inhibition is sufficient to explain the effects of PETIC." (PMID 28881649, 2017). "The USP1/UAF1 complex is emerging as a novel target in cancer therapy, but several aspects of its function and regulation remain to be further clarified." (PMID 25744535, 2015). "In complex with its cofactor UAF1, the USP1 deubiquitinase plays an important role in cellular processes related to cancer, including the response to DNA damage." (PMID 25744535, 2015). "We also summarize USP1 alterations found in cancer, combining data from the literature and public databases with our own data." (PMID 23937906, 2013). "Regarding its potential as a target for cancer therapy, the inhibition of USP1 as a strategy to modulate the efficacy of cisplatin and other DNA damaging drugs warrants further investigation." (PMID 23937906, 2013). "Inhibiting the function of the USP1/UAF1 complex sensitizes cancer cells to chemotherapy, suggesting that this complex is a relevant anticancer target." (PMID 22701671, 2012). "USP1 plays a significant role in immunotherapy, particularly in the context of cancer treatment." (PMID 40001543, 2025). "In the present study, we revealed that USP1 may inhibit NK cell-mediated immune responses in cancer cells." (PMID 39735674, 2025). "Additionally, SJB2-043 has been found to impede the maintenance of cancer stem cells and DNA damage repair by modulating USP1 activity." (PMID 40136409, 2025). "Moreover, USP1 can deubiquitinate and stabilize DNA-binding protein inhibitors, which play vital roles in various cancer-related processes, including cell differentiation, migration, invasion, and metastasis." (PMID 39735674, 2025). "Moreover, using the CCLE database, we observed that USP1 expression was the most elevated in SCLC cell lines compared to any other type of cancer cell lines." (PMID 39735674, 2025). "Ongoing clinical trials suggest that USP inhibitors, particularly those targeting USP1, may have the potential to become valuable components of cancer therapy." (PMID 40001543, 2025). "Notably, the ongoing phase I clinical trial (NCT05240898) is assessing the safety and effectiveness of KSQ-4279, a USP1 inhibitor, in patients with advanced cancer." (PMID 39735674, 2025). "AlkB homolog 5 (ALKBH5) could be demethylated by N6 -methyladenosine (m6A) and this process has been found to promote cancer development in humans and enhance the stability of USP1 mRNA." (PMID 39048945, 2024). "In view of these considerations, a detailed understanding of how the neuronal APC/C differentially regulates USP1 protein levels may be important for developing cancer and neurodegeneration treatments." (PMID 38932933, 2024). "Based on this mechanism of action, combinatorial therapy with both USP1 and PARP inhibitors may have clinical efficacy in BRCA1-deficient cancers with acquired resistance to PARP inhibitors." (PMID 38201233, 2023). "Notably, the USP1-specific inhibitor ML323—originally developed to sensitize cancer cells to DNA-damaging agents—decreased adipocyte differentiation and lipid accumulation in 3T3-L1 cells without cytotoxicity." (PMID 38012162, 2023). "Together, these findings suggest that Hsp90, MAST1 and USP1 may be excellent targets for cisplatin-resistant cancer cells, as their inhibition will enhance cisplatin sensitivity and result in increased cell death." (PMID 37569286, 2023). "While USP1’s function remains conservative across different types of cancer, its downstream targets may vary." (PMID 37821462, 2023). "In multiple cancers, USP1 has been identified as a key oncogene." (PMID 35923700, 2022).
cancer (continued). "In addition, USP1 is upregulated in multiple cancers, like osteosarcoma, breast cancer, hepatic carcinoma and colorectal cancer." (PMID 35663242, 2022). "Overall, our findings elucidate a mechanism for steady-state USP1 autocleavage in maintaining replication fork integrity and, thus, inform new therapeutic strategies to exploit the cellular intolerance of protein-DNA trapping lesions for cancer treatments." (PMID 35365626, 2022). "USP1 was reported to play an oncogenic role in multiple cancers via diverse mechanisms." (PMID 35307036, 2022). "Overall, our results suggest that the pharmacological inhibition of both MAST1 and USP1 could mitigate cisplatin-resistance in cancerous tumors." (PMID 35966591, 2022). "Ubiquitin specific peptidase 1 (USP1), a member of the DUBs, usually forms with a complex with USP1-associated factor 1 (UAF1, also known as WDR48) and plays a key role in promoting the development of some cancers." (PMID 34154657, 2021). "Cumulative evidences have shown the abnormal overexpression of USP1 in malignant tumors 6,12,13." (PMID 33390793, 2021). "We found that most types of cancers displayed USP1 positive staining." (PMID 32951278, 2020). "In present, the mechanisms underlying USP1 overexpression in human cancer is still not fully understood." (PMID 32951278, 2020). "Regarding USP1 autocleavage, co-expression of the C90S and GG/AA mutants did not result in cleavage, while the cancer-associated mutation L669P was found to reduce cleavage efficiency." (PMID 25744535, 2015). "To determine if any of these cancer-associated mutations might alter USP1 cleavage, we used site-directed mutagenesis to introduce each of these amino acid changes into GFP-USP1, and we co-expressed these proteins with Xpress-UAF1 in 293T cells." (PMID 25744535, 2015). "As Usp1-null mice have been shown to be hypersensitive to DNA damage it is likely that targeting Usp1 could increase the sensitivity of cancer cells to DNA damaging agents." (PMID 25962961, 2015). "The USP1/UAF1 complex is emerging as a novel target for cancer treatment, and inhibitors of USP1 catalytic activity have been reported to reverse the resistance to platinum-based chemotherapeutic drugs in NSCLC cells and to inhibit the growth of leukemic cell lines." (PMID 25744535, 2015). "The development and implementation of USP1-targeted therapies will benefit from a more detailed knowledge of how the function of this DUB is regulated, and how this regulation can be affected by cancer-related mutations." (PMID 25744535, 2015). "These double mutants also failed to undergo cleavage when expressed in combination with GFP-USP1GG/AA, suggesting that the cancer-related mutations tested here do not alter the cis/trans mode of cleavage of USP1." (PMID 25744535, 2015). "Mutational alteration of human DUBs, including USP1, does not appear to be a frequent event in cancer." (PMID 23937906, 2013). "In this regard, a survey of publically available cancer microarray expression data using the Oncomine Research Edition database reveals that USP1 mRNA expression has been found to be significantly altered (Fold change > 1.5; P-value < 0.05) in several tumor types." (PMID 23937906, 2013). "Ubiquitination of FANCD2 and PCNA is important for their roles in DNA repair, suggesting that subversion of USP1 in human cancers might impinge on transformation events through alterations of DNA repair pathways." (PMID 21283576, 2011). "USP1 has been linked to cancer development and metastasis but not yet to trastuzumab resistance." (PMID 38534787, 2024). "This suggests that FA‐ and/or USP1‐ targeting inhibitors may be beneficial for cancer therapy." (PMID 36385258, 2023). "Accordingly, USP1 could be a therapeutic target for the treatment of cancer." (PMID 36352191, 2023). "Therefore, understanding the specific targets and effects of USP1 in each cancer type could lead to innovative therapeutic opportunities." (PMID 37821462, 2023).